INS (insulin)
Diseases named in the same sentence as INS in open-access papers (continued):
Sharing a sentence is not in itself a finding about the gene and the disease.
Insulin resistance (continued). "We also found a suggestion of higher insulin resistance reflected in associations with higher insulin levels (% difference (95% CI) = 11.5 (−0.40, 25.0) μU/mL) and higher HOMA-IR (% difference (95% CI) = 9.10 (−2.30, 21.8) U), neither of which was statistically significant." (PMID 33824455, 2022). "Additionally, propionic acid intake has been reported to exert a beneficial effect on insulin sensitivity modulated by it inhibitory effect on free fatty acids’ metabolism as well as inflammation associated with insulin resistance." (PMID 36364395, 2022). "The action of GLP-1 may favor myocardial glucose uptake regardless the insulin secretion via, ameliorating insulin resistance associated with HF though the up-regulation of GLP-1 isoforms such as sarcolemmal and endosome Glut4." (PMID 35813629, 2022). "Neurodegenerative disorders, and AD in particular, are associated with T2DM-like metabolic abnormalities and insulin resistance in the brain, due to which intranasal insulin, insulin sensitizers, and GLP-1R agonists have been considered as potential therapeutic options in AD treatment." (PMID 35008973, 2022). "Therefore, compared to the general population, patients with insulin resistance present difficulty in metabolizing blood glucose, which causes the pancreas to produce more insulin to facilitate the entry of glucose into the cells." (PMID 36140201, 2022). "Thus, vitamin D deficiency inhibits pancreatic secretion of insulin and it is associated with insulin resistance." (PMID 35406129, 2022). "First, given that neuronal insulin resistance and Tau hyperphosphorylation mutually enhance each other, this suggests that the decrease in neurotrophin receptor expression was caused by impaired insulin-signaling." (PMID 36117625, 2022). "In particular, high levels of PGRN inhibit insulin signaling and glucose uptake both in vitro and in vivo and may be involved in the development of obesity-associated insulin resistance, while deficiency of PGRN provides protective action in this condition." (PMID 35432201, 2022). "Diabetes, obesity, and cancer frequently coexist in part due to insulin resistance where excessive stimulation of the insulin/insulin-like growth factor (IGF-1) pathway might cause abnormal cell signaling and cancer growth." (PMID 35455439, 2022). "Both insulin resistance and insulin deficiency can cause a decrease in insulin signals in the skeletal muscle, affect the regulation of skeletal muscle protein balance, and may cause a decline in skeletal muscle quality." (PMID 35001531, 2022). "Interestingly, vaccenic acid levels were higher in men with hyperglycemic-hyperinsulinemic than in men with normoglycemic-normoinsulinemic, and were positively associated with both fasting insulin and homeostatic model assessment for insulin resistance." (PMID 35983485, 2022). "The increase in fasting plasma glucose, fasting insulin, and homeostasis model assessment of insulin resistance (HOMA-IR) caused by HFD feeding decreased after BBR treatment; in addition, Bifidobacterium and Lactobacillus were enriched and E. coli was inhibited after BBR treatment." (PMID 36105164, 2022). "Insulin resistance is associated with the loss of the suppressive effects of insulin." (PMID 36359273, 2022). "Another cause of hyperuricemia is insulin resistance and high plasma insulin concentrations." (PMID 35743665, 2022). "Also, a study (2015) reported that lipid accumulation in the liver stimulates the secretion of pro-inflammatory factors (TNF-ɑ, IL-6), thus reducing insulin signaling, which ultimately causes more lipid accumulation and insulin resistance." (PMID 36159326, 2022). "Several studies have found that abnormally high expression of hepatic miRNA 29a in high-fat diet and genetic animal models is causally linked to insulin resistance, hyperlipidemia, and prevents insulin from downregulating PEPCK, resulting in unrestrained gluconeogenesis." (PMID 36160451, 2022).
Insulin resistance (continued). "Changes in endothelial permeability and diminished peripheral blood flow caused by hypertension may limit insulin release and promote insulin resistance in metabolically active tissues." (PMID 36440203, 2022). "Alternatively, adipose tissue insulin resistance caused by pregnancy may have limited our ability to demonstrate any effect of administered sEVs on adipose insulin signaling in the current study." (PMID 36239315, 2022). "Indeed the overproduction of insulin by beta-cells in an effort to compensate for the insulin resistance causes an important ER stress in beta-cells that activates the NLRP3 inflammasome pathway leading to IL-1B production." (PMID 36247456, 2022). "Insulin signaling loss in the liver results in severe insulin resistance and hepatic dysfunction." (PMID 36570152, 2022). "T2DM is due to a progressive loss of adequate β-cell insulin secretion and insulin resistance." (PMID 35694215, 2022). "When insulin is deficient or IR is abnormal, a large amount of glucose cannot enter the cells, is stored in the body, and is eliminated in the urine, the cornerstones of insulin resistance and type 2 diabetes." (PMID 36611803, 2022). "The interaction between the two risk factors may suggest that impaired beta cells cannot produce enough insulin to cope with increased insulin resistance as caused by high palmitate acids, thereby triggering a high risk of GDM." (PMID 36183068, 2022). "Impaired insulin signaling is a well-known cause for insulin resistance." (PMID 35768470, 2022). "Furthermore, using LIRKO mouse as a model of pure insulin resistance in hepatocytes associated with hyperinsulinemia, we show that chronic insulin exposure requires the activation of insulin receptor signaling pathways to induce hepatic cellular senescence." (PMID 35872305, 2022). "In humans, serum OC was reported to be decreased in patients with type 2 diabetes compared to the levels in nondiabetic controls; inversely associated with blood glucose levels, HbA1c, BMI and insulin resistance; and positively associated with insulin secretion and insulin sensitivity." (PMID 35321337, 2022). "Nicotine exposure could also induce a reduction in insulin release, and negatively affect insulin action, suggesting that nicotine could be a cause for the development of insulin resistance." (PMID 34539539, 2021). "Low muscle mass may also be associated with insulin resistance, as muscles are the target site of insulin-mediated glucose action, which is an additional risk factor for developing treatment complications." (PMID 34684550, 2021). "Dyslipidemia in this population indicates that obesity can affect insulin secretion or may result in insulin resistance, which may explain this association." (PMID 34938332, 2021). "However, many unsolved issues still hinder the role of IGFBP2 in insulin sensitivity and insulin resistance, and the suggested the association with type 2 diabetes, which we discuss below." (PMID 33498859, 2021). "Since then, additional mutations in the mtDNA have been associated with elevated fasting insulin, increased fasting plasma glucose, increased Homeostatic Model Assessment of Insulin Resistance (HOMA-IR) values, as well as type 2 diabetes and metabolic syndrome." (PMID 34370595, 2021). "Insulin has been implicated to induce ferritin synthesis at mRNA level in experimental models, proposing a novel explanation for the hyperferritinemia commonly seen upon insulin resistance." (PMID 34067164, 2021). "Suppressed insulin secretion and β-cells apoptosis may concur with insulin resistance to glucocorticoid-associated hyperglycemia." (PMID 33800138, 2021). "A range of additional metabolic factors could additionally be adjusted for, e.g. glucose, insulin or insulin resistance, but with the risk of overadjustment of regression models and multicolinearity." (PMID 33504912, 2021).
Insulin resistance (continued). "While these effects on insulin resistance may depend on the “baseline drift,” understanding how it affects and causes the “baseline drift” in the crosstalk with insulin regulation is a challenge in the next decade." (PMID 35111696, 2021). "Insulin resistance is associated with metabolic inflexibility, highlighting that altered mitochondrial function may contribute to reduced insulin sensitivity via reduced oxidative capacity." (PMID 34069950, 2021). "In addition, ATF6α deficiency can improve insulin sensitivity and restrain the development of insulin resistance." (PMID 33688365, 2021). "Indeed, the cardiometabolic markers consistently reported to be improved by IF like serum lipid and insulin levels as well as insulin resistance are those closely linked to AT inflammation." (PMID 33897419, 2021). "In addition, obesity-induced hyperglycemia can cause insulin resistance, a condition induced by the impairment of insulin-induced glucose uptake in insulin-sensitive tissues." (PMID 34579347, 2021). "Besides SNPs in AMY1 gene, several SNPs in susceptibility genes have been associated to insulin sensitivity or insulin resistance." (PMID 34408213, 2021). "Regarding the neuroprotective effects of insulin in the brain, and the probable causative role of insulin resistance in PD pathogenesis, emerging studies continue to demonstrate the beneficial effects of intranasal (IN) insulin in both animal models of PD and humans in clinical trials." (PMID 33497031, 2021). "It has become increasingly evident that insulin resistance is often associated with the proinflammatory cytokine response in insulin-sensitive tissues including the liver, which may lead to a decreased insulin sensitivity." (PMID 34745386, 2021). "Insulin treatment was confirmed to reduce insulin resistance, but the underlying mechanism remains unknown." (PMID 34917687, 2021). "The increased susceptibility to diet-induced obesity despite protection against the development of insulin resistance might be attributed to the reduced lipolysis efficiency and improved insulin secretory response in A-FABP-deficient mice." (PMID 34502295, 2021). "Thus, our study points towards a role for insulin action and resistance in tanycytes possibly contributing to multiple manifestations of obesity-associated insulin resistance." (PMID 34931084, 2021). "In addition, obesity is the main cause of insulin resistance, which can lead to the increase of the expression levels of insulin and insulin-like growth factor (IGF)." (PMID 34485124, 2021). "Additional studies are required to explore the underlying mechanism by which the regulation of insulin resistance or insulin secretion could be involved." (PMID 34938332, 2021). "Moreover, maternal 1- and 2-h PG levels have been found to be independently associated with insulin resistance and impaired insulin secretion also during childhood." (PMID 34108933, 2021). "Interestingly, TMAO downregulates the hepatic insulin signaling cascade, but beneficially reduces oxidative and ER stress associated with insulin resistance." (PMID 34445033, 2021). "Finally, note that insulin resistance can involve and eventually lead to deficiencies and demise of insulin‐producing β‐cells in pancreatic islets, and, vice versa, deficiencies of insulin secretion can produce extra‐pancreatic insulin resistance." (PMID 34766133, 2021). "C57bl6/J adult mice treated for four weeks with corticosterone exhibit severe insulin resistance associated with expansion of the beta cell mass both by proliferation and neogenesis, as well as increased insulin secretion at a basal state and in response to glucose stimulation." (PMID 33435513, 2021). "However, insulin resistance was shown to be implicated in AD pathogenesis and diminished insulin signaling have been detected in the brains of AD patients." (PMID 34366841, 2021).
Insulin resistance (continued). "Obesity, characterized by an uncontrolled inflammatory response, decreased antioxidative capacity, compromised insulin sensitivity, and dysfunctional angiogenesis, is associated with metabolic diseases including insulin resistance, T2DM, and cardiovascular diseases." (PMID 35052597, 2021). "Significant associations were observed for variants in the adiposity cluster with body mass index (BMI), waist circumference and breast cancer, and variants in the insulin-resistant cluster with fasting insulin, glucose values, and homeostatic model assessment of insulin resistance (HOMA-IR)." (PMID 34207127, 2021). "Finally, a higher HbA1c level means a higher glucose status, a sign of insufficient insulin effect or the underlying insulin resistance." (PMID 33778026, 2021). "We next tested whether insulin resistance was the underpinning mechanism of vitamin B6 deficiency-induced glucose intolerance by performing insulin tolerance testing (ITT) in GD 12.5 and 16.5 dams." (PMID 33772108, 2021). "Hence, despite the fact that both adiponectin and visfatin have insulin-mimetic effects, their association with obesity, insulin resistance and cardiovascular disease seems to go in opposite directions, thus of particular interest to study." (PMID 34779349, 2021). "Genes encoding additional insulin signalling/mTORC1 pathway proteins were also significantly differentially expressed between the virgin and pregnant mice, all in a direction consistent with insulin resistance/reduced mTORC1 signalling." (PMID 33808370, 2021). "The pronounced obesity-related hyperinsulinemia and insulin resistance in Pima Indians may have obscured the association of fasting insulin with markers of CVD risk." (PMID 34746266, 2021). "However, a decrease in insulin sensitivity due to the disruption of various molecular pathways causes insulin resistance (IR)." (PMID 33919190, 2021). "Previous investigations have revealed that proinflammatory cytokines such as TNF-α and IL-6 could impair insulin signaling, which may cause insulin resistance." (PMID 34371867, 2021). "The high fasting insulin levels associated with obesity mediated insulin resistance, in turn determine arterial stiffness and CV outcomes in women than men, while increasing insulin resistance was associated with greater increase in arterial stiffness in women and not in men." (PMID 34441775, 2021). "One explanation for the suppression of lipogenic process by ethanol exposure is that ethanol and/or its metabolites impair insulin release and cause insulin resistance, and further inhibit the AKT signaling which is required for the activation of SREPB1c and the lipogenic pathway in the liver." (PMID 34267188, 2021). "Furthermore, interventions that improve insulin sensitivity (rosiglitazone, weight loss, exercise) were found to increase insulin clearance, suggesting that insulin resistance suppresses insulin clearance." (PMID 34206745, 2021). "Type 2 diabetes is caused by impaired insulin secretion and/or insulin resistance." (PMID 33918379, 2021). "Consistent with the fetal insulin hypothesis, infants with severe congenital insulin resistance secondary to loss-of-function mutations in the insulin receptor gene, INSR, have very low birthweights." (PMID 33569631, 2021). "In the duration of NAFLD, an increased lipid accumulation in hepatic parenchyma makes glucose metabolism worse and causes suppression of insulin secretion, which promotes IR; hence, the liver degeneration has a connection with changes in peripheral and hepatic insulin resistance development." (PMID 34830360, 2021). "Therefore, evidence suggests that peripheral insulin resistance is associated with impaired brain insulin action, although the mechanisms remain to be elucidated." (PMID 33597002, 2021). "In addition, increased insulin resistance (IR) and treatment with exogenous insulin therapy is positively associated with higher BMD and increased fragility fractures." (PMID 34572351, 2021).
Insulin resistance (continued). "The daily feeding cycle results in the rise and fall of nutrient fluxes and hormonal levels in the body, which results in the observation that components in the diets may modulate insulin action and can cause insulin resistance." (PMID 34440929, 2021). "Several GWAS have identified variants positioned in the GIPR locus, including the E354Q GIPR variant, to associate with increased 2-h glucose levels, decreased insulin secretion, insulin resistance and risk of T2D, further supporting the importance of the GIP-GIPR axis in glucose regulation." (PMID 34760890, 2021). "A low insulin dose generally represents underinsulinization and could cause symptoms of insulin deficiency, while a high insulin dose resembles an insulin resistance status." (PMID 33099763, 2021). "Moreover, moderately elevated ferritin levels are linked with increased insulin resistance, reduced insulin secretion, and T2DM." (PMID 34722008, 2021). "Antenatal glucocorticoid therapy is also linked to higher plasma insulin concentrations in subjects 30 years of age, which might result in insulin resistance later in life." (PMID 33481865, 2021). "In addition to the progressive loss of the pancreatic capacity to produce insulin, numerous studies have shown that carbohydrate intolerance associated with aging is mainly due to insulin resistance." (PMID 34356299, 2021). "Additionally, adiponectin is strongly related to insulin sensitivity, so a decrease in adiponectin causes an increase in insulin resistance." (PMID 33532616, 2021). "Deficient post receptor insulin signaling is the key characteristic involved in insulin resistance." (PMID 34833905, 2021). "Hyperprolactinemia is associated with insulin resistance which improves with dopamine agonist therapy which might be related to the therapy associated weight loss and an activation of insulin signaling." (PMID 33995272, 2021). "However, similarly to what has been observed for clitoral PI, uterine PI appeared to be positively correlated to several parameters linked to glucose homeostasis and insulin resistance, specifically fasting insulin, HbA1c and HOMA-IR." (PMID 34552164, 2021). "At the molecular level, insulin resistance is the consequence of insulin signaling impairment resulting from mutations or post-translation modification of the insulin receptor (IR) itself or any of its downstream effectors, including the insulin receptor substrate (IRS) proteins, PI3K, and Akt." (PMID 33562475, 2021). "It has been reported that through increasing lipid synthesis, oxidation, and sugar transport through insulin and the affinity for insulin receptors, polyunsaturated phospholipids could be associated with insulin resistance." (PMID 34122100, 2021). "Destruction of the β-cells with detection of auto-antibodies is a hallmark of type 1 diabetes characterized by early onset of the disease and immediate insulin dependency, while late onset type 2 diabetes is primarily associated with insulin resistance and a progressive loss of β-cell function." (PMID 35008750, 2021). "Furthermore, obesity and insulin resistance increased the risk of liver cancers, and our previous study suggested that inactivation of p65 in mouse livers improved insulin sensitivity through the cAMP/PKA pathway." (PMID 34380537, 2021). "Increased synthesis of FXII, FXI and FIX in hepatocytes along with a shorter activated partial thromboplastin time (APTT) were observed in patients with impaired insulin sensitivity, probably mediated by a low-grade inflammatory reaction caused by insulin resistance." (PMID 34072487, 2021). "More importantly, insulin resistance may be the key cause leading to increased risk of carotid atherosclerosis in insulin-treated T2DM patients in the present study." (PMID 33598483, 2021). "The progressive loss of β-cell insulin secretion along with insulin resistance accounts for T2DM." (PMID 34445765, 2021).